CORO1C (coronin 1C)
Diseases named in the same sentence as CORO1C in open-access papers (continued):
Sharing a sentence is not in itself a finding about the gene and the disease.
breast carcinoma (10 papers, 2017 to 2025). "In conclusion, the association between YB-1 and coronin-1C provides a novel pathway which could be a potential therapeutic target in breast cancer metastasis." (PMID 28302118, 2017). "The association between YB-1 and coronin-1C offers a novel approach by which metastasis of breast cancer cells could be targeted and abrogated." (PMID 28302118, 2017). "Lastly, in breast cancer, YBX1 gene silencing reduces the expression of CORO1C gene and inhibits the migration and invasion potential of breast cancer cells." (PMID 40799245, 2025). "In breast cancer cells, CORO1C was found to be involved in invadopodia formation and MT1-MMP surface trafficking and to promote invasiveness." (PMID 37239355, 2023). "Studies have shown that CORO1C promotes the metastases of breast cancer and lung squamous cell carcinoma." (PMID 32487167, 2020). "CORO1C was previously reported to promote metastasis in breast cancer and lung squamous cell carcinoma." (PMID 30974047, 2019). "A previous report has found that non-coding RNAs such as microRNAs are directly involved in the transcriptional regulation of coronin-1C in breast cancer." (PMID 28302118, 2017). "It is reported that miR-206 represses the migration of breast cancer cells via the post-transcriptional regulation of CORO1C." (PMID 28159933, 2017). "Indeed, some experiments using either RNAi depletion or over-expression in cell lines show that Coronin 1C is a positive regulator of proliferation and invasion in breast cancer and lung-squamous cell carcinoma." (PMID 32686704, 2020). "Knocking down of CORO1C inhibited metastasis of human breast cancer cells." (PMID 30974047, 2019). "Silencing of CORO1C induced a significant decrease in cell migration (52.6%) and cell invasion (63.9%) in MDA-MB-231 breast cancer cells." (PMID 28302118, 2017). "In breast cancer MDA-MB-231 cells, YBX1 could regulate invasion and migration by regulating its downstream target CORO1C." (PMID 32695668, 2020). "Western blot data indicated that miR-1 overexpression significantly downregulated WASF2, TWF1, CNN3, TMSB4X and CORO1C, showing that miR-1 could inhibit breast cancer cell metastasis by targeting the WASF2, TWF1, CNN3, TMSB4X and CORO1C genes." (PMID 28159933, 2017). "For breast cancer, YBX1 has been regarded as potential biomarker with poor outcome and silencing YBX1 could inhibit invasive potential through binding its downstream target, such as CORO1C and MMP1." (PMID 34991621, 2022).
hepatocellular carcinoma (10 papers, 2010 to 2023). A malignant tumor that arises from hepatocytes. "High levels of CORO1C were associated with poor prognosis in human hepatocellular carcinoma patients 8 and primary effusion lymphoma patients." (PMID 30974047, 2019). "This is in agreement with previous research indicating a similar role of miR-133a-3p and its interaction with CORO1C in hepatocellular carcinomas." (PMID 36649032, 2023). "As a target of several microRNAs, CORO1C promotes cell proliferation, invasion, and migration in non-small lung cancer, hepatocellular carcinoma, and triple-negative breast cancer." (PMID 34179087, 2021). "The knockdown of CORO1C impairs cell polarity and cytoskeleton in hepatocellular carcinoma cells." (PMID 34179087, 2021). "Furthermore, CORO1C is differentially expressed in various solid tumors, such as glioblastoma cancer, hepatocellular cancer, breast cancer and lung cancer." (PMID 34179087, 2021). "Hepatocellular carcinoma patients with positive expression of CORO1C showed a worse clinical stage compared with patients with negative CORO1C expression." (PMID 30974047, 2019). "Coro1C expression has been found to be elevated in hepatocellular carcinoma and malignant glioblastoma, and expression has been found to correlate with motility in a number of cancer cell lines, whereas knockdown of Coro1C has a negative effect on fibroblast migration." (PMID 25925950, 2015).
glioblastoma (8 papers, 2010 to 2023). The most malignant astrocytic tumor (WHO grade IV). "The overexpression of CORO1C in aggressive solid tumours such as glioblastomas and head and neck cancers are often associated with its metastatic powers." (PMID 36649032, 2023). "The aim of this study was to in silico analyse the expression profiles of CORO1C in glioblastomas and to identify its diagnostic or prognostic potential." (PMID 36649032, 2023). "Previous research has identified that CORO1C is expressed significantly within migrating cells and its silencing demonstrated reduced proliferation and migration velocity within the glioblastoma cell lines A172 and U373." (PMID 36649032, 2023). "In the current study, overexpression of CORO1C in both adult and pediatric glioblastomas was observed." (PMID 36649032, 2023). "The current in silico investigation demonstrated that the overexpression of CORO1C appeared to be a distinctive feature for solid and highly malignant tumours of different origins, including glioblastomas." (PMID 36649032, 2023). "The frequent up- or down-regulation of CORO1C observed in microarray experiments of different cancer types, such as in glioblastomas and colorectal cancer (CRC) suggested that the protein is highly transcriptionally dynamic." (PMID 36649032, 2023). "Overexpression of CORO1C has been reported in various solid tumors, including glioblastoma, hepatocellular, breast, lung, gastric, and colorectal cancers." (PMID 34884487, 2021). "Further, functional analyses by coronin-1C knockdown revealed the roles of coronin-1C in regulating cell proliferation, migration, invadopodia formation, and invasion in glioblastoma cells." (PMID 20181269, 2010). "However, there is limited information on how CORO1C regulates these processes within glioblastoma patients." (PMID 36649032, 2023). "However, recent data using genetic deletion of Coronin 1C in a GEM model of glioblastoma showed no change in time of survival with or without Coronin 1C88, further supporting the idea that Coronin 1C impacts tumor progression differently between cancer types." (PMID 32686704, 2020).
colorectal cancer (7 papers, 2021 to 2023). A primary or metastatic malignant neoplasm that affects the colon or rectum. "In colorectal cancer, high expression of CORO1C is associated with malignant phenotypes, such as lymph node and distant metastases." (PMID 34884487, 2021). "In colorectal cancer cells, CORO1C interacted with trophoblast cell surface protein 2, and CORO1C overexpression enhanced cancer phenotypes via the PI3K/AKT signaling pathway." (PMID 37239355, 2023). "One report has indicated that the PI3K/AKT signaling pathway is significantly inhibited by CORO1C knockdown in colorectal cancer." (PMID 35692390, 2022).
lymph node metastasis (4 papers, 2012 to 2023). "The CORO1C expression was associated with histological type, lymph node metastases, distant metastases, AJCC stage, venous invasion, and perineural invasion, indicating the aggressive characteristic of the cancer type." (PMID 34179087, 2021). "The expression of CORO1C was associated with histological type, lymph node metastasis, distant metastasis, AJCC stage, venous invasion, and perineural invasion." (PMID 34179087, 2021).
non-small cell lung carcinoma (4 papers, 2023 to 2025). A group of at least three distinct histological types of lung cancer, including non-small cell squamous cell carcinoma, adenocarcinoma, and large cell carcinoma. "The association between miR-206 and CORO1C has been demonstrated in non-small lung cell carcinomas and triple-negative breast cancer, where deletion or inhibition of CORO1C rescued the expression levels of miR-206 and led to supressed metastasis." (PMID 40596133, 2025). "Coronin 1C (CORO1C) regulates apoptosis and cell cycle progression, acting as an oncogene in ccRCC and non-small-cell lung cancers." (PMID 38673800, 2024). "The oncogenic properties of CORO1C have been described in several types of cancer, including colorectal and liver cancers, non-small cell lung carcinoma, and melanomas." (PMID 36649032, 2023). "Demonstrated repressed proliferative and invasive properties of miR-206 within the non-small cell lung carcinoma (NSCLC) cell line A549 suggested that the overexpression of CORO1C was suppressed." (PMID 36649032, 2023).
triple-negative breast carcinoma (4 papers, 2020 to 2025). An invasive breast carcinoma which is negative for expression of estrogen receptor (ER), progesterone receptor (PR), and human epidermal growth factor receptor 2 (HER2). "In triple-negative breast cancer (TNBC) cells, miR-206 inhibits cancer cell migration by directly targeting CORO1C, which regulates actin filaments." (PMID 32695668, 2020).
bladder cancer (3 papers, 2020 to 2022). "It's evident that CORO1C overexpression was highly associated with advanced disease and worse clinical status in bladder cancer." (PMID 32695668, 2020). "In our study, the high expression level of CORO1C also predicted poor survival outcomes in bladder cancer, which is consistent with other cancer types." (PMID 32695668, 2020). "We downloaded another online data set, GSE19915, which included 144 bladder cancer patients to test the prognostic performance of these genes, but only three genes (CORO1C, TMPRSS4, and ZNF692) could match the probes in later survival analysis." (PMID 32695668, 2020). "We infer that CORO1C may induce EMT in bladder cancer cells by increasing neutrophil activity." (PMID 32695668, 2020). "CORO1C and TMPRSS4 might be two meaningful clinical indicators in bladder cancer but appear to have opposite prognostic value." (PMID 32695668, 2020). "The total alteration frequency is included to illustrate that CORO1C and TMPRSS4 are altered in 4.2% cases, which looks relatively not much higher in bladder cancer." (PMID 32695668, 2020).
glioma (3 papers, 2010 to 2023). A benign or malignant brain and spinal cord tumor that arises from glial cells (astrocytes, oligodendrocytes, ependymal cells). "An experimental setting comprised from both in vitro and in vivo studies, demonstrated that CORO1C could promote glioma growth via the Wnt/β-catenin signalling pathway." (PMID 36649032, 2023).
lung squamous cell carcinoma (3 papers, 2019 to 2020). "In lung squamous cell carcinoma, CORO1C was identified as a target of the miR-1/133a cluster, and silencing CORO1C inhibited cancer cell proliferation, migration, and invasion." (PMID 32695668, 2020).
Obesity (3 papers, 2021 to 2022). Accumulation of substantial excess body fat. "Among them, CORO1C, a gene recently identified to be up-regulated in the SAT of individuals with obesity, was found to be closely linked to %TWL and was also identified as hypomethylated." (PMID 35739539, 2022). "It has been reported that CORO1C (coronin 1C) were highly expressed in adipose tissues, and it might be critical genes in the development and prognosis of obesity." (PMID 36088304, 2022). "It was found that the mRNA expression levels of STAT3, CORO1C, SERPINH1, MVP and ITGB5 were significantly increased in the obesity compared with the control group." (PMID 34248836, 2021).
brain tumour (2 papers, 2023 to 2025). "Malignant brain tumours, in general, expressed higher CORO1C levels than normal and adjacent normal tissues, with these differences reaching statistical significance." (PMID 40596133, 2025). "Previous evidence has revealed that CORO1C exerts its effects via F-actin turnover during the processes of neurite overgrowth and migration of brain tumour cells." (PMID 36649032, 2023). "A CBTTC dataset of the expression of CORO1C in different paediatric brain tumours depending on their histologic subtype was also incorporated in this research." (PMID 36649032, 2023). "We demonstrated that the CORO1C mRNA expression was elevated within specific brain regions and within paediatric GBM patients, associated with highly aggressive brain neoplasms, suggesting that it potentially possesses oncogenic properties." (PMID 36649032, 2023). "Coronin 1C (CORO1C) is a key player in actin rearrangement and cofilin dynamics, as well as enhancing the processes of neurite overgrowth and migration of brain tumour cells." (PMID 36649032, 2023). "Further analysis of CORO1C expression within normal and cancerous brain samples confirmed that CORO1C was significantly overexpressed within the brain tumour cohort, p < 0.01." (PMID 36649032, 2023). "We further validated the upregulation of CORO1C in MB and GB cells lines, suggesting that its overexpression could enhance the early identification of paediatric and adult brain tumours and serve as therapeutic targets for their management." (PMID 40596133, 2025). "The elevated expression levels of CORO1C and SV2B suggested that they could serve as putative prognostic biomarkers, enhancing their clinical relevance in combating highly malignant brain tumours like MB and GB." (PMID 40596133, 2025).
liver cancer (2 papers, 2010 to 2023). An epithelial or non-epithelial malignant neoplasm that arises from the liver. "Increasing coronin-1C expression was found in liver cancer tissues of HCCLM9-nude mice with spontaneous pulmonary metastasis." (PMID 20181269, 2010). "Elevated coronin-1C expression was observed in liver cancer tissues of HCCLM9-nude mice, with highly lung metastasis rate 100%, compared with MHCC97L-nude mice, with no lung metastasis." (PMID 20181269, 2010). "Coronin-1C level showed a marked upsurge at the end of fifth wk when pulmonary metastasis occurred, implying coronin-1C might indeed predict liver cancer progression and lung metastasis." (PMID 20181269, 2010).
melanoma (2 papers, 2020 to 2023). A malignant, usually aggressive tumor composed of atypical, neoplastic melanocytes. "By combining this model and tumor initiation protocol with a conditional knockout allele, we evaluated the role of Coronin 1C in melanoma progression and metastasis." (PMID 32686704, 2020). "We postulate that the unique metastatic nature of melanoma and the underlying biology of melanocytes may help explain the context-dependent nature of Coronin 1C function in disease progression and metastasis." (PMID 32686704, 2020). "For instance, high expression of CORO1C has been observed in melanomas when compared to normal skin tissue." (PMID 36649032, 2023). "Here, we combined a conditional knockout of Coronin 1C with a genetically engineered mouse model of PTEN/BRAF-driven melanoma." (PMID 32686704, 2020). "To test the role of Coronin 1C in melanoma growth and metastasis, we modified an existing GEM model by breeding in a Coronin 1C conditional knockout allele." (PMID 32686704, 2020). "Interestingly, these vesicles contain melanosome markers suggesting a melanoma-specific mechanism of EV release, regulated by Coronin 1C, that contributes to the high rates of metastasis in melanoma." (PMID 32686704, 2020). "Coronin 1C is overexpressed in multiple tumors, leading to the widely held view that this gene drives tumor progression, but this hypothesis has not been rigorously tested in melanoma." (PMID 32686704, 2020).
atherosclerosis (1 paper, 2018). A disease characterized by the build-up of fatty material and calcium deposition in the arterial wall resulting in partial or complete occlusion of the arterial lumen. "Coronin 1c has been proposed to interact with subunits of NADP oxidase —this enzyme uses NADPH to generate superoxide and thereby plays an important role in fighting against microbial infections and in the pathology of atherosclerosis." (PMID 30521565, 2018).
benign brain neoplasms (1 paper, 2023). "They specifically showed that in normal brain tissue, the expression of CORO1C in cortex neurons was significantly reduced, whereas high grade benign brain neoplasms expressed increased levels of the protein." (PMID 36649032, 2023).
bladder tumor (1 paper, 2020). "In summary, this result elucidates that there is a high possibility of the participation of CORO1C and TMPRSS4 in the bladder tumor cell EMT based on the opposite effects, which suggested their different roles during disease metastatic course." (PMID 32695668, 2020).
brain neoplasms (1 paper, 2023). A neoplasm (disease) that involves the brain. "The overall expression levels of CORO1C within PLGG, DIPG, CRANIO, PTEN, ES, DNT, and CPP paediatric brain cancer subtypes were significantly lower in comparison to the expression of the protein found in HPGG." (PMID 36649032, 2023).
C. perfringens infection (1 paper, 2021). "Following C. perfringens infection, some genes in the host intestinal mucosa were differentially down-regulated, for example, Coronin-1C, Receptor Protein-Tyrosine Phosphatases (RPTPs), and Prosaposin." (PMID 34959561, 2021).
colorectal adenocarcinoma (1 paper, 2022). The most common type of colorectal carcinoma. "A total of 961, 500, and 500 tumors as well as 836, 413, and 434 paracarcinoma normal tissues from 993, 509, and 509 subjects with colorectal adenocarcinoma were informative for CORO1C, RAD23B, and ARPC5, respectively." (PMID 35589723, 2022).
head and neck squamous cell carcinoma (1 paper, 2020). A squamous cell carcinoma that arises from any of the following anatomic sites: lip and oral cavity, nasal cavity, paranasal sinuses, pharynx, larynx, and salivary glands. "In head and neck squamous cell carcinoma cells, Coronin 1B, a coronin with significant homology to Coronin 1C, has been shown to regulate exosome secretion via destabilization of the actin network at MVB docking sites through interactions with cortactin and Rab27a71." (PMID 32686704, 2020).
lung carcinoma (1 paper, 2020). "In this study, we showed that CORO1C was upregulated in NSCLC tissues as well as a series of lung cancer cell lines." (PMID 32206066, 2020). "Similar to the q-RT-PCR result in tissues, CORO1C was upregulated in the five lung cancer cell lines compared with BEAS-2B cells." (PMID 32206066, 2020). "In addition, we detected CORO1C expression in BEAS-2B cells and the five lung cancer cell lines." (PMID 32206066, 2020).
metastatic melanoma (1 paper, 2022). A melanoma that has spread from its primary site to another anatomic site. "In fact, it has been shown that TIAM1 and CORO1C are negative regulators of metastatic melanoma growth." (PMID 35562405, 2022).
metastatic tumor (1 paper, 2017). "TRFC was shown originally to be significantly induced in DU145 cells, CORO1C/coronin was found to be induced in androgen-insensitive PCa and S100A16 appears to be upregulated only in metastatic tumor cells." (PMID 28163933, 2017).
nasopharyngeal carcinoma (1 paper, 2020). A carcinoma arising from the nasopharyngeal epithelium. "In nasopharyngeal carcinoma, CORO1C promotes cancer cell migration and invasion by induction of EMT." (PMID 32695668, 2020).
oral squamous cell carcinoma (1 paper, 2021). "The Cancer Genome Atlas (TCGA) analysis revealed that CORO1C, CORO2A, and CORO7 were significantly upregulated in oral squamous cell carcinoma (OSCC) tissues (p < 0.05)." (PMID 34884487, 2021).
osteosarcoma (1 paper, 2023). A usually aggressive malignant bone-forming mesenchymal neoplasm, predominantly affecting adolescents and young adults. "An interaction between miR-9-5p and CORO1C has been observed but not demonstrated in osteosarcoma pathogenesis." (PMID 36649032, 2023).
pancreatic ductal adenocarcinoma (1 paper, 2023). An infiltrating adenocarcinoma that arises from the epithelial cells of the pancreas. "Analysis of large cohort data from The Cancer Genome Atlas revealed that expression of CORO1A, CORO1B, CORO1C, CORO2A, and CORO7 was significantly upregulated in pancreatic ductal adenocarcinoma (PDAC) tissues (p < 0.05)." (PMID 37239355, 2023).